VEZT (vezatin, adherens junctions transmembrane protein)
Description:
Plays a pivotal role in the establishment of adherens junctions and their maintenance in adult life. Required for morphogenesis of the preimplantation embryo, and for the implantation process. (Microbial infection) In case of Listeria infection, promotes bacterial internalization by participating in myosin VIIa recruitment to the entry site.
Synonyms: DKFZP761C241; VEZATIN
Tractability: Antibody: UniProt places it where antibodies can reach, with high confidence; UniProt predicts a signal peptide or a membrane-spanning region; its Gene Ontology location is reachable by antibodies, with medium confidence. PROTAC: ubiquitination databases record sites on it; its protein half-life has been measured.
Gene: Protein-coding gene on chromosome 12 (95,217,746 to 95,302,799, forward strand). Ensembl gene ENSG00000028203.
Subcellular location: Cell membrane; Cell projection, stereocilium membrane; Cell junction, adherens junction; Nucleus; Cytoplasmic vesicle, secretory vesicle, acrosome
Subcellular location (Human Protein Atlas): Nucleoplasm; Cytosol
Gene Ontology:
Molecular function: myosin binding
Biological process: cell-cell adhesion
Cellular component: nucleoplasm; plasma membrane; nucleus; stereocilia ankle link complex; acrosomal vesicle; adherens junction; stereocilium membrane
Genetic constraint (gnomAD): Loss-of-function variants: 38 observed, 73.59 expected, observed/expected ratio (o/e) 0.52, 90% interval 0.4 to 0.68. The upper end of that interval is the gene's LOEUF score, 0.68, which puts it in group 2 of 6, group 1 being the genes least tolerant of losing a copy. Missense variants: 814 observed, 857.91 expected, observed/expected ratio (o/e) 0.95, 90% interval 0.89 to 1. Synonymous variants: 318 observed, 318.71 expected, observed/expected ratio (o/e) 1, 90% interval 0.91 to 1.1.
Homologues: Orthologues: chimpanzee VEZT (99% identical), macaque VEZT (99% identical), dog VEZT (92% identical), pig VEZT (91% identical), rabbit VEZT (90% identical), mouse Vezt (84% identical), guinea pig VEZT (79% identical), rat Vezt (69% identical), tropical clawed frog vezt (56% identical), zebrafish vezt (44% identical).
Diseases named in the same sentence as VEZT in open-access papers:
VEZT is named in the same sentence as 15 diseases in open-access papers, as found by Europe PMC text mining. Sharing a sentence is not in itself a finding about the gene and the disease. The quoted sentences say what the papers report.
endometriosis (14 papers, 2017 to 2026). The growth of functional endometrial tissue in anatomic sites outside the uterine body. "VEZT (rs10859871) is linked to cell adhesion and has shown positive association with endometriosis in several studies, suggesting a potential role in lesion attachment and implantation." (PMID 41415877, 2025). "A locus near the VEZT gene has been significantly linked to endometriosis in the general population, highlighting the role of specific genetic variants in the disease’s progression." (PMID 41009445, 2025). "In relation to endometriosis, several studies have reported association of endometriosis risk with increased expression of VEZT and FGD6." (PMID 37443771, 2023). "In 2016 Holdsworth-Carson and coworkers demonstrated that this SNP acts as an eQTL especially in endometrial tissue of endometriosis patients, with the A allele at rs14121 apparently inducing an overexpression of VEZT, and an opposite effect of rs10859871." (PMID 34298916, 2021). "In the blood and endometrium, the C allele at risk of endometriosis of rs10859871 SNP in previous works was associated with increased expression of VEZT, and a pathogenetic role had been hypothetically attributed to this over-expression of VEZT." (PMID 32143537, 2020). "VEZT was identified in a recent endometriosis meta-analysis as a potential casual gene from its association with an eQTL in blood, however, heterogeneity in the region suggested there was no single casual SNP in this instance." (PMID 30061686, 2018). "Significant heterogeneity (PHEIDI=0.004) for rs14,121 was observed, suggesting that the observed causal effect of VEZT expression on risk of endometriosis may be due to colocalization, but this needs to be investigated further." (PMID 28537267, 2017). "Risk variants for endometriosis on chromosome 6p25.1 are located in regulatory regions near oestrogen receptor 1 (ESR1) and both VEZT and FGD6 on chromosome 12q22 have roles in cell adhesion." (PMID 36304015, 2021). "The choice of which polymorphisms were to be analysed fell to WNT4, VEZT and FSHB genes because of their hypothetical correlation with endometriosis, according to recent findings in the literature." (PMID 32143537, 2020). "Keywords included: endometriosis combined with genes, genetics, SNPs, genome-wide association study (GWAS), WNT4, VEZT, FSHB, next-generation sequencing (NGS) and epigenetics." (PMID 32143537, 2020). "In particular, a recent study investigated in a Greek population three of these SNPs: rs7521902, rs10859871 and rs11031006, mapped respectively on WNT4, VEZT and FSHB genes, highlighting a significant association with endometriosis." (PMID 32143537, 2020). "Two cis-eQTLs overlap genomic regions associated with endometriosis with good evidence for the causal SNP in each region influencing endometriosis risk and the expression of LINC00339 on chromosome 1 or expression of VEZT on chromosome 12." (PMID 30061686, 2018). "The SMR analysis identified two potential causal genes, CDC42 (rs2268177; PSMR=1.07 × 10−12) and VEZT (rs14121; PSMR=3.41 × 10−6), underlying endometriosis loci at 1p36.12 and 12q22, respectively." (PMID 28537267, 2017). "Genetic studies have identified nine loci associated with endometriosis, six of which (rs12700667 at 7p15.2, rs7521902 near WNT4, rs10859871 near VEZT, rs1537377 near CDKN2B-AS1, rs7739264 near ID4, and rs13394619 in GREBI) were confirmed as genome-wide significant." (PMID 41009445, 2025). "Considering the studied physiological roles of VEZT, its potential for a functional role in endometriosis is a likely option, since VEZT has been demonstrated to be upregulated in ectopic endometrium with respect to eutopic endometrium in patients suffering from endometriosis." (PMID 32143537, 2020).
gastric cancer (3 papers, 2013 to 2022). A primary or metastatic malignant neoplasm involving the stomach. "Vezatin, adherens junctions transmembrane protein (VEZT) has been identified as a tumor suppressor gene in gastric cancer." (PMID 35923577, 2022). "The frequent silencing or downregulation of VEZT in gastric cancer cell lines suggests that it is likely a tumor-suppressor gene in our previous study." (PMID 24069310, 2013). "VEZT expression is markedly downregulated and regulated epigenetically by DNA methylation in gastric cancer cells." (PMID 24069310, 2013). "We further analyzed the methylation of VEZT in tissues and corresponding blood of gastric cancer patients." (PMID 24069310, 2013). "Promoter methylation was demonstrated to mediate the transcriptional silence of VEZT gene in gastric cancer cell lines." (PMID 24069310, 2013). "We examined the methylation level of the VEZT promoter in 30 tissue samples DNA from patients with primary gastric cancer tissues, corresponding plasma DNA and the control using BSP methods, which covered the regions of -171bp to -428bp." (PMID 24069310, 2013). "To examine the reproducibility of our findings, we assessed the ability of NCI-N87 gastric cancer cells to invade, migrate and form tubular structures upon VEZT overexpression." (PMID 24069310, 2013). "Primary gastric cancer tissues showed higher methylation levels in the VEZT promoter region when compared with normal gastric tissues (P < 0.05)." (PMID 24069310, 2013). "Relationship between VEZT expression levels in cancer tissues and clinicopathological factors in patients with gastric cancer." (PMID 24069310, 2013). "Using bisulfate sequencing polymerase chain reaction methods, the results showed that VEZT was hypermethylated in gastric cancer patients when compared with healthy controls." (PMID 24069310, 2013). "Inactivation of the VEZT gene has been identified in gastric cancer, and the methylation of CpG islands within the promoter region of the VEZT gene contribute to its inactivation as determined by a previous study conducted by our lab." (PMID 24069310, 2013). "We investigated the relationship between VEZT expression levels in 104 paired gastric cancer tissues and clinicopathological factors in patients with gastric cancer." (PMID 24069310, 2013). "Bisulfate sequencing polymerase chain reaction (BSP) methods showed that VEZT was hypermethylated in tissues and corresponding blood of gastric cancer patients compared with healthy controls." (PMID 24069310, 2013). "Hypermethylation of VEZT detected in the peripheral blood of gastric cancer patients suggests a biomarker potential for gastric cancer." (PMID 24069310, 2013). "In order to test this point, we screened VEZT expression in several gastric cancer cell lines by real-time PCR and western blot." (PMID 24069310, 2013). "We also examined the capacity of gastric cancer cells overexpressing VEZT to invade and migrate by the transwell invasion and migration assays." (PMID 24069310, 2013). "The mean methylated levels of VEZT in 30 primary gastric cancer tissues and 30 normal gastric tissues were 67.78 ± 25.90% and 42.42 ± 30.30%, respectively." (PMID 24069310, 2013). "Prior to this study, very little was known about VEZT expression in gastric carcinoma and its correlation with the clinicopathologic features of these patients." (PMID 24069310, 2013). "Previous studies found that HPP1, VEZT and IFITM3, which contain a similar transmembrane domain to that of TMEM196, were hypermethylated associated with downregulation in colorectal cancer, gastric cancer and melanoma, respectively." (PMID 26056045, 2015). "The level of methylated VEZT in tissues and plasma could serve as a molecular marker for gastric cancer." (PMID 24069310, 2013). "VEZT possesses important functions for the suppression of gastric cancer." (PMID 24069310, 2013). "The mechanism of the methylation and the exact role of VEZT in the development of gastric cancer are currently unknown." (PMID 24069310, 2013).
gastric cancer (continued). "We aimed to clarify the epigenetic regulation and biological functions of VEZT in gastric cancer." (PMID 24069310, 2013). "Based on a previous study from our lab, we postulated that the methylation of VEZT promoter was different in gastric carcinoma patients and healthy controls; we used online bioinformatics software to analyze the promoter region and methylation status of the VEZT gene." (PMID 24069310, 2013). "Restoring VEZT activity may be a potential strategy for gastric cancer treatment." (PMID 24069310, 2013). "Restoring VEZT expression in MKN-45 and NCI-N87 gastric cancer cells inhibited growth, invasion and tumorigenesis in vitro and in vivo." (PMID 24069310, 2013). "In this study, we show that the expression level of VEZT is involved in lymphatic metastasis, depth of cancer invasion and TNM stage in 104 gastric cancer patients." (PMID 24069310, 2013). "In cell biology experiments, we constructed a VEZT-expressing vector and restored VEZT expression in MKN-45 and NCI-N87 gastric cancer cells for gain-of-function study." (PMID 24069310, 2013). "We compared changes in gene expression profiles in gastric cancer cells with or without VEZT gene transfection and identified a set of VEZT target genes." (PMID 24069310, 2013). "We constructed a pEGFP-N1-VEZT expression vector and transfected pEGFP-N1 vector into the gastric cancer cell line MKN-45 and NCI-N87, which showed no or low level of VEZT expression." (PMID 24069310, 2013).
choroideremia (1 paper, 2014). Choroideremia (CHM) is an X-linked chorioretinal dystrophy characterized by progressive degeneration of the choroid, retinal pigment epithelium (RPE) and retina. "They included 9 USH genes, 2 candidate USH genes (VEZT and PDZD7), seven hearing-loss genes and the choroideremia-causative gene CHM and the sequencing was carried out on Roche GS Junior sequencer." (PMID 25404053, 2014).
chronic gastritis (1 paper, 2013). Inflammation of the stomach that is chronic in nature. "At first, we examined the methylation level of the VEZT promoter in the DNA from 23 tissue samples from patients with H. pylori-positive chronic gastritis and the controls using BSP and MSP methods, which covered the regions of -171bp to -428bp and -342 bp to -513 bp, respectively." (PMID 24069310, 2013). "The promoter region of VEZT was generally methylated in patients with chronic gastritis according to MSP analysis; however, we found four cases of H. pylori-positive chronic gastritis that were relatively unmethylated." (PMID 24069310, 2013).
gastric tumor (1 paper, 2013). "In a previous study, we revealed VEZT was downregulated in gastric tumor samples by RT-PCR, the down-expression levels of VEZT was further revealed to be associated with methylation." (PMID 24069310, 2013).
cancer (4 papers, 2013 to 2018). A tumor composed of atypical neoplastic, often pleomorphic cells that invade other tissues. "We found that the expression level of VEZT was associated significantly with lymphatic metastasis, depth of cancer invasion and TNM stage (P < 0.05)." (PMID 24069310, 2013). "Only limited data existed regarding a functional association between the VEZT gene and human cancer." (PMID 24069310, 2013). "The selected small activating RNA (saRNA) also inhibited the growth, invasion and migration of GC cells by specially reactivating vezatin (VEZT), which resulted in an obvious decrease in the proliferative, invasive and migratory abilities of cancer cells." (PMID 29471827, 2018). "The tumor suppressive role of VEZT expression was apparent in both cancer cell lines tested (P < 0.01), suggesting that VEZT suppresses the tumorigenicity of cancer cells." (PMID 24069310, 2013). "This study provides novel insight into the regulation of the VEZT gene, which could represent a potential target for therapeutic anti-cancer strategies." (PMID 24069310, 2013).
tumor (3 papers, 2013 to 2022). "To clarify the possible mechanism of VEZT’s tumor-inhibiting function, we screened the target genes regulated by VEZT." (PMID 24069310, 2013). "Next, we examined the effect of VEZT overexpression on tumor growth by inoculating MKN-45 or NCI-N87/N1 and VEZT/N1 cells subcutaneously into the right flank regions of nude mice." (PMID 24069310, 2013). "Recently, we have identified, an adherens junctions transmembrane protein, VEZT as a candidate tumor-suppressor gene." (PMID 24069310, 2013). "The mechanism of the tumor suppressor effect of VEZT overexpression could be explained by a set of target genes identified by global microarray analysis and confirmed by real-time PCR and chromatin immunoprecipitation assay." (PMID 24069310, 2013). "Several single nucleotide polymorphism (SNPs) have been associated with the disease, for example in the region of the wingless-type mammalian mouse tumor integration site family member 4 (WNT4), vezatin (VEZT) and follicle stimulating hormone beta polypeptide (FSHB)." (PMID 34544404, 2021).
infection (1 paper, 2014). The state of being infected such as from the introduction of a foreign agent such as serum, vaccine, antigenic substance or organism. "We also found VEZT and MYO7A in S. rosetta and Dictyostelium where they may serve to internalize bacteria for feeding or other non-infection purposes." (PMID 25395670, 2014).
VEZT also shares sentences with these, for which no sentence is quoted: colon cancer (1 paper); colorectal cancer (1); hearing (1); melanoma (1); ovarian tumour (1); thyroid cancer (1); Usher syndrome (1).